PRKAR1A (protein kinase cAMP-dependent type I regulatory subunit alpha)
Diseases named in the same sentence as PRKAR1A in open-access papers (continued):
Sharing a sentence is not in itself a finding about the gene and the disease.
acromegaly (8 papers, 2014 to 2026). Acromegaly is an acquired disorder related to excessive production of growth hormone (GH) and characterized by progressive somatic disfigurement (mainly involving the face and extremities) and systemic manifestations. "The present study reports on a novel PRKAR1A insertion mutation in a patient with acromegaly and left atrial myxoma in CNC." (PMID 25298879, 2014). "The patient was diagnosed to have the rare CNC syndrome characterized by recurrent atrial myxoma and acromegaly due to a novel 22 bp insertion mutation in PRKAR1A which was predicted to be deleterious by in silico analysis." (PMID 25298879, 2014). "However, without genetic studies on gene mutations (e.g., AIP, PRKAR1A, GPR101, GNAS, MEN1, CDKN1B, SDHx, MAX, it is difficult to assess whether OL-23/77 was affected by gigantism and acromegaly or just one of these diseases." (PMID 35498425, 2022).
adrenal tumors (7 papers, 2016 to 2025). "As a genetic modifying factor for the development of testicular and adrenal tumors in patients with germline PRKAR1A mutation, PDE11A is probably a phenotype modifying gene but not a causative gene." (PMID 39006359, 2024). "In tumors associated with CNC as well as in thyroid and adrenal tumors with downregulation of PRKAR1A, allelic losses of the 17q22–24 PRKAR1A chromosomal locus are frequently identified and are associated with changes in PKA activity." (PMID 34359735, 2021). "A previous study demonstrated that PDEs can act as phenotype modifiers, leading to adrenal tumors in Carney complex patients carrying PRKAR1A variant." (PMID 32098292, 2020). "Moreover, inactivating mutations in PRKAR1A, initially described in Carney complex, can result in constitutive activation of the cAMP–protein kinase A pathway, leading to cortisol-producing adrenal tumors in sporadic cases." (PMID 41007858, 2025). "Vaduva and coworkers emphasized that several potent molecular mutations might contribute to the progression of CS and adrenal tumors, and they especially focused on PRKAR1A germline-inactivating alterations." (PMID 36583008, 2022). "Overall, immunohistochemical analysis revealed higher expression of StAR in adrenal tumors with mutations in PRKACA, GNAS, and PRKAR1A than in wild-type tumors, which exhibited lower expression of StAR." (PMID 27606678, 2016). "PRKAR1A defects have not been identified in PBMAH, however somatic losses of the 17q22–24 region in PBMAH lead to PKA subunit and enzymatic activity changes and altered PKA signaling that is similar to that of other adrenal tumors with PRKAR1A defects or 17q losses." (PMID 33776926, 2021).
adrenocortical tumors (6 papers, 2015 to 2022). "Furthermore, somatic inactivating variants in GNAS and PRKAR1A have been found in sporadic adrenocortical tumors." (PMID 36105398, 2022). "In addition, a number of in vitro and transgenic mouse studies have demonstrated that PRKAR1A is an adrenocortical tumor suppressor gene and its inactivation leads to ACTH-independent cortisol secretion." (PMID 26042218, 2015). "Furthermore, in a cohort of patients with adrenocortical tumors without variants in PRKAR1A, GNAS, or PDE11A, 7 patients harbored variants in PDE8B." (PMID 36105398, 2022). "Furthermore, in a study of samples from 27 patients with adrenocortical tumors without mutations in GNAS, PRKAR1A, PDE11A, or PDE8B, abnormalities of the cAMP-signaling pathway were found, with mutation-negative ACAs having significantly decreased PDE activity." (PMID 30456751, 2018).
melanoma (6 papers, 2017 to 2025). A malignant, usually aggressive tumor composed of atypical, neoplastic melanocytes. "Loss of PRKAR1A protein may have value in distinguishing melanotic schwannoma from metastatic melanoma; classical melanomas have shown retained protein expression of PRKAR1A, whereas 7 of 21 melanotic schwannomas had loss of PRKAR1A." (PMID 28973408, 2017). "Although mutations affecting PRKAR1A and MAPK21 are reported in some melanomas, alterations in PRKCA are uncommon in malignant melanomas." (PMID 34943205, 2021). "A study was subsequently carried out at another immunohistochemistry center for the protein kinase A regulatory subunit 1 alpha (PRKAR1A), which demonstrated negativity in melanoma cells." (PMID 34287308, 2021). "On the other hand, when TERT promoter mutations are present, regardless of PRKAR1A status, melanomas should be considered." (PMID 34943205, 2021).
meningioma (6 papers, 2019 to 2024). A generally slow growing tumor attached to the dura mater. "Interestingly, amplification of the long arm of chromosome 17 was found in anaplastic meningiomas, in proximity of the locus hosting PRKAR1A gene, encoding for PKA RIAlpha, suggesting a possible link to its expression." (PMID 31671850, 2019). "Interestingly, recurrent mutation in PRKAR1A has been reported in few meningioma cases with non-mutated NF2 gene." (PMID 31671850, 2019). "Next, a database reporting the expression level of different genes in 68 meningioma cases was interrogated with BioGPS to explore the relationship between PRKACA gene, coding for PKA CAT, and PKA regulatory subunits (PRKAR1A, PRKAR1B, PRKAR2A, and PRKAR2B) gene products." (PMID 31671850, 2019).
schwannoma (6 papers, 2011 to 2025). A benign, usually encapsulated slow growing tumor composed of Schwann cells. "Mice haploinsufficient for a null allele of Prkar1a (Prkar1a+/−) developed tumors, mainly bone tail and thyroid tumors and schwannomas, but the spectrum was somewhat different from that seen in humans." (PMID 26608815, 2015). "Previous studies showed that complete inactivation of the Prkar1a subunit (coding for RIα) in the germline leads to embryonic lethality, while Prkar1a–deficient mice are viable and develop schwannomas, thyroid, and bone neoplasms, and rarely lymphomas and sarcomas." (PMID 26608815, 2015). "Although reported in Prkar1a heterozygous mice, the presence of nonpigmented schwannomas is consistent with our conclusion that the cancer is a mucinous malignant neurogenic tumor arising in association with CNC." (PMID 40777560, 2025). "Prkar1a +/− mice develop nonpigmented schwannomas and fibrotic bone lesions beginning at about 6 months of age; 10% of the mice subsequently develop thyroid tumors." (PMID 40777560, 2025).
thyroid tumor (6 papers, 2008 to 2025). A benign or malignant neoplasm affecting the thyroid gland. "Identifying the genetic basis of PRKAR1A-associated thyroid tumors is important as it will provide better clinical management to these patients." (PMID 34359735, 2021). "The CNC patients with PRKAR1A genetic mutation were more susceptible to the occurrence of thyroid tumors, and about two thirds of these cases showed thyroid disorder in infancy or adolescence." (PMID 29666959, 2018). "Furthermore, the lesions were associated with allelic loss of the Prkar1a locus on chromosome 11 as it happens in thyroid tumors with PRKAR1A mutations." (PMID 34359735, 2021). "Further evidence to support the involvement of PKA in thyroid tumors was demonstrated by studying the PRKAR1A gene in thyroid tissue from patients with CNC." (PMID 34359735, 2021). "It was also observed that patients with no mutations of the PRKAR1A gene or its genomic locus 17q22–24, were less likely to develop thyroid tumors." (PMID 34359735, 2021). "The results suggested that PRKAR1A is indeed involved in sporadic thyroid tumors, along with other genes, some of which could be associated with the PKA pathway." (PMID 34359735, 2021). "In addition, thyroid tumors (p = 0.016) were more frequent in PRKAR1A carriers and presented at a younger age (p = 0.03)." (PMID 34359735, 2021).
heart failure (5 papers, 2020 to 2024). Inability of the heart to pump blood at an adequate rate to meet tissue metabolic requirements. "It is estimated that more than 50% of mortality related to CNC is attributed to cardiovascular complications such as heart failure, indicating a potential role of PRKAR1A in the maintenance of heart function and morphology." (PMID 32212257, 2020).
lung adenocarcinoma (5 papers, 2015 to 2024). A carcinoma that arises from the lung and is characterized by the presence of malignant glandular epithelial cells. "Previous studies strongly suggested that PRKAR1A dysregulation caused endocrine neoplasia, which was speculated to rely on tissues; however, its role in epithelium-generated tumors was rarely reported, especially in lung adenocarcinoma." (PMID 27995993, 2016). "We used shRNA, for the first time, to inactivate PRKAR1A in lung adenocarcinoma cells and observed that PRKAR1A deletion enhanced in vivo lung metastasis in nude mice." (PMID 27995993, 2016). "Taken together, this study provided strong evidence that PRKAR1A positively regulated E-cadherin expression in human lung adenocarcinoma." (PMID 27995993, 2016). "Taken together, our data indicated that downregulation PRKAR1A expression profile correlates with poor prognosis in lung adenocarcinoma after the operation." (PMID 27995993, 2016). "We tested the classic tumor proliferation and metastasis function of PRKAR1A in lung adenocarcinoma cells by both in vitro and in vivo assays." (PMID 27995993, 2016). "Our data showed that PRKAR1A deletion increased the proliferation and migration of lung adenocarcinoma cells and that decreased levels of PRKAR1A led E-cadherin upregulation to reasonably conjecture that PRKAR1A was an anti-oncogene in the lung." (PMID 27995993, 2016). "In order to elucidate the role of PRKAR1A in lung adenocarcinoma, we compared the expression of PRKAR1A mRNA and protein with the adjacent normal lung tissues." (PMID 27995993, 2016). "To determine the clinical significance of PRKAR1A in lung adenocarcinomas, we investigated the expression of PRKAR1A in 102 specimen pairs of frozen adenocarcinomas and cognate normal lung tissues which were 5 cm distant from the tumor margins." (PMID 27995993, 2016). "PRKAR1A mRNA was correlated with CDH1 expression in lung adenocarcinoma tissues (r = 0.3814, P < 0.0001)." (PMID 27995993, 2016). "Next, we examined the correlation between PRKAR1A and E-cadherin mRNA and protein level by analyzing 102 lung adenocarcinoma tissues from our lung tumor tissue repository, of all the patients who underwent surgical resection." (PMID 27995993, 2016). "In summary, the present study revealed the biological function and clinical significance of PRKAR1A as a suppressor in lung adenocarcinoma." (PMID 27995993, 2016). "Then, we assessed the expression levels of PRKAR1A and E-cadherin proteins in the same 102 lung adenocarcinoma specimens by immunohistochemistry." (PMID 27995993, 2016). "The expression of PRKAR1A is downregulated in lung adenocarcinomas." (PMID 37452081, 2023). "The pharmaceutical intervention of PRKAR1A might provide a promising treatment to alleviate lung adenocarcinoma progression." (PMID 27995993, 2016). "Compared with normal lung tissues, the primary lung adenocarcinomas exhibited low PRKAR1A levels." (PMID 27995993, 2016). "Collectively, through the modulation of ERK/Snail/E-cadherin signaling pathway, PRKAR1A could act as a tumor suppressor gene by inhibiting lung adenocarcinoma growth and metastasis." (PMID 27995993, 2016). "Furthermore, we investigated the correlation between the expression PRKAR1A and E-cadherin in order to explore the role of PRKAR1A in epithelial-mesenchymal transition (EMT) of lung adenocarcinoma proliferation and metastasis." (PMID 27995993, 2016). "Analyses of public databases revealed that PRKAR1A was downregulated in human lung adenocarcinoma." (PMID 27995993, 2016). "Furthermore, we compared the protein levels of PRKAR1A in clinically collected human lung adenocarcinoma specimens and paired adjacent normal tissues using immunoblotting (western blotting)." (PMID 27995993, 2016). "Overall, our data suggested that PRKAR1A could inhibit the proliferation and migration of lung adenocarcinoma cells." (PMID 27995993, 2016). "Previously, we first found that PRKAR1A was downregulated in lung adenocarcinoma patients." (PMID 27995993, 2016).
lung adenocarcinoma (continued). "Importantly, in our clinicopathological analysis, a positive correlation was established between PRKAR1A and E-cadherin in lung adenocarcinomas." (PMID 27995993, 2016). "We demonstrated that elevated E-cadherin in shPRKAR1A-induced cells could partially relieve proliferation and migration, thereby extrapolating that E-cadherin was an essential target for PRKAR1A in the regulation of lung adenocarcinoma cells’ proliferation and metastatic behavior." (PMID 27995993, 2016). "Our data demonstrated that PRKAR1A fits the putative definition of an anti-oncogene in the lung and that it regulated ERK/Snail signaling pathway in lung adenocarcinoma cells." (PMID 27995993, 2016).
multiple endocrine neoplasia type 1 (5 papers, 2007 to 2025). An autosomal dominant tumor predisposition syndrome caused by pathogenic variants in the MEN1 gene, characterized by an increased risk of tumors of the parathyroid glands, pituitary gland, and foregut neuroendocrine tumors (most commonly pancreatic islet cells). "The patient underwent genetic testing for Cowden syndrome (PTEN gene), Carney complex (PRKAR1A gene), and multiple endocrine neoplasia syndrome type 1 (MEN1 gene); no deleterious mutations were identified." (PMID 17411461, 2007).
pituitary tumor (5 papers, 2016 to 2024). A benign or malignant neoplasm affecting the pituitary gland. "To date, homologous deletions of 10 different genes, which are Men1, Cdkn1b, Prkar1a, Rb, Cdkn2b (encoding p19), Drd2, Cdkn2c (encoding p18), Aip, Prl and Prlr, have been reported to yield mouse knockout models for pituitary tumours." (PMID 26320859, 2016). "This profile is similar to that of sporadic PITs but differs from that of other hereditary pituitary tumors (due to GNAS, AIP, or PRKAR1A defects) that secrete primarily GH." (PMID 31263451, 2019).
pseudohypoparathyroidism (5 papers, 2016 to 2025). "ASD has since been reported as a phenotypic feature of acrodysostosis type 2 (associated with PRKAR1A and PDE4D genes) and pseudohypoparathyroidism (associated with GNAS gene)." (PMID 40917827, 2025).
bone tumors (4 papers, 2014 to 2021). "As previously demonstrated in bone tumors arising in human patients with a PRKAR1A mutation, tumoral osteoblasts from the Prkar1a+/− mice showed a significantly elevated level of both a total and a free PKA enzyme." (PMID 34440460, 2021). "In this manuscript, we analyzed bone tumors arising from mice with activated PKA caused by mutation of the PKA regulatory subunit Prkar1a." (PMID 25299576, 2014). "In this report, we describe alterations in β-catenin that are observed in bone tumors arising from mice with mutations in Prkar1a as a means to activate PKA signaling." (PMID 25299576, 2014). "To assess the functional interaction of PKA and β-catenin targets, we turned to data we had previously generated on mRNA transcripts altered in Prkar1a+/− bone tumors." (PMID 25299576, 2014). "Distribution of TCF and CREB binding sites in genes with altered transcription in Prkar1a+/− bone tumors*." (PMID 25299576, 2014). "We previously reported that approximately 80% of Prkar1a+/− mice develop osteoblastic bone tumors by one year of age and primary cultures of tumoral bones showed increased PKA activity and decreased osteoblastic differentiation compared to cells isolated from control animals." (PMID 25299576, 2014). "Analysis of the genes altered in bone tumors from Prkar1a+/− mice also suggest the cooperation of the cAMP-responsive transcription factor CREB and β-catenin, as binding sites for CREB and TCF strongly tended to occur together in the promoters of genes with altered transcription in the tumors." (PMID 25299576, 2014).
cardiac tumor (4 papers, 2020 to 2025). "Genetic analysis of this case showed multiple mutations within the PRKAR1A gene in tissue samples from both the brain metastasis and cardiac tumor, which provides further evidence that PRKAR1A mutation can occur in sporadic cardiac myxomas." (PMID 38310436, 2023). "However, mice displaying cardiac-specific heterozygous ablation of PRKAR1A show no signs of cardiac tumor formation but instead diminished cardiomyocyte hypertrophy and augmented cardiomyocyte necrosis." (PMID 39966109, 2025).
glioma (4 papers, 2021 to 2024). A benign or malignant brain and spinal cord tumor that arises from glial cells (astrocytes, oligodendrocytes, ependymal cells). "In terms of kinin-related genes, we observed that the transcriptional activity of PRKAR1A, which encodes protein kinase A (PKA), is upregulated in grade G3-G4 gliomas." (PMID 38254732, 2024). "Our results suggest that the assessment of mRNA BDKRB1, PRKAR1A, MAP2K2, and EGFR by RT-qPCR in samples of patients with gliomas may have diagnostic significance." (PMID 38254732, 2024). "The average numbers of PRKAR1A mRNA copies in glioma G3 patients (Me = 602,700.25 copies/μg RNA), as well as in glioma G4 patients (Me = 548,360.50 copies/μg RNA), were significantly higher compared to G2 grade (Me = 327,519.69 copies/μg RNA) (p = 0.029 and p = 0.003, respectively)." (PMID 38254732, 2024). "In addition, increased levels of MIR-29a and MIR-92a within the hypoxic glioma-derived EVs decrease the expression of the high-mobility group box transcription factor 1 (Hbp1) and protein kinase CAMP-dependent type I regulatory subunit alpha (Prkar1α) genes in MDSCs, respectively." (PMID 36010994, 2022).
lung carcinoma (4 papers, 2012 to 2022). "What’s more, they found four target genes of miR-155 including HBP1, TJP1, SMAD5 and PRKAR1A involved in the oxidative stress process of lung cancer." (PMID 31727002, 2019). "Our results provided an impetus to further investigate PRKAR1A in ERK/Snail signaling in lung cancer." (PMID 27995993, 2016). "For example, BMPR2, BRD7, PRKAG2, PRKAR1A and PPP2R2A (PP2A Bα subunit B55α), which are differentially expressed between group V (H+V−S+[M/T]) and groups II/IV (H+V+S−/H+V−S+[M]), play roles in tobacco-mediated lung diseases and lung cancers." (PMID 35642061, 2022). "In this cluster, NT5C2, API5, CPN, PRKAR1A and COPB1 were fully down-regulated in lung cancer." (PMID 23122428, 2012).
sarcoma (4 papers, 2015 to 2022). A usually aggressive malignant neoplasm of the soft tissue or bone.
adrenocortical adenoma (3 papers, 2015 to 2022). "There are also some intriguing genetic interactions between PRKAR1A and PDE11A in the pathogenesis of adrenal cortical adenomas." (PMID 36313756, 2022).